COL1A2 (collagen type I alpha 2 chain)
Diseases named in the same sentence as COL1A2 in open-access papers (continued):
Sharing a sentence is not in itself a finding about the gene and the disease.
lactic acidosis (1 paper, 2023). Metabolic acidosis characterized by the accumulation of lactate in the body. "On the contrary, lactic acidosis increased the expression levels of typical myofibroblast-related genes, such as ACTA2 (i.e., gene encoding α-SMA), COL1A1, and COL1A2, which were 2.5-fold, 3-fold, and 4-fold increased, respectively, compared to the basal conditions." (PMID 36980280, 2023). "Briefly, we demonstrated that acADSCs grown under lactic acidosis conditions lose the adipocyte differentiation markers FABP4, C/EBPα, adiponectin, and perilipin-1 while acquiring the myofibroblast markers α-SMA, COL1A1, and COL1A2." (PMID 36980280, 2023).
lipoblastoma (1 paper, 2020). A lipoma usually occurring in the extremities of young children (usually boys). "Molecular genetic examinations of lipoblastomas revealed rearrangements of 8q11∼q13, hyaluronic acid synthase 2 (HAS2) and collagen 1 alpha 2 (COL1A2) as well as pleomorphic adenoma gene 1 (PLAG1) amplification." (PMID 31282548, 2020).
malignant astrocytomas (1 paper, 2020). "In addition, the close association observed here between increased VEGFA and COL1A2, COL3A1 and COL1A1 expression in GBM, might also contribute to explain the effect of VEGFA on inducing collagenase expression and remodeling the tumor microenvironment in malignant astrocytomas (i.e. GBM)." (PMID 32647207, 2020).
malocclusion (1 paper, 2025). "Candidate genes such as COL1A2, matrix metalloproteinases (MMP-1, MMP-9), and muscle-related genes (ACTN2, ACTN3) have been implicated in craniofacial morphology and malocclusion risk." (PMID 41153339, 2025).
metastatic cancer (1 paper, 2024). A carcinoma which has spread from the original site of growth to another anatomic site. "More specifically and importantly, COL1A1, COL1A2, and FAP were all highly expressed in metastatic cancer tissues, possibly indicated a higher chance of metastasis when abnormally expressed, which have not been reported before." (PMID 39034310, 2024).
mucinous adenocarcinoma (1 paper, 2022). An invasive adenocarcinoma composed of malignant glandular cells which contain intracytoplasmic mucin. "Patients with mucinous adenocarcinoma had remarkably higher COL1A2 mRNA expression than those with adenocarcinoma (P < 0.05)." (PMID 36057263, 2022).
mucinous ovarian cancer (1 paper, 2018). An invasive malignant neoplasm that arises from the ovary and is characterized by the presence of malignant epithelial cells that contain intracytoplasmic mucin and may resemble the epithelial cells of the endocervix or gastrointestinal tract. "The immunohistochemical analysis of LOX, COL1A2, COL3A1, COL21A1, and ALDH1A1 was performed for few cases of endometrioid, serous, and mucinous ovarian cancer in order to verify the localization of analyzed proteins in the real cancer tissue." (PMID 30583585, 2018).
multiple epiphyseal dysplasia (1 paper, 2009). Multiple epiphyseal dysplasias (MED/EDMs) are characterized by epiphyseal anomalies causing joint pain early in life, recurrent osteochondritis and early arthrosis. "The genes implicating BMD variation and multiple epiphyseal dysplasias (MED) like COL1A1, COL1A2, CO9A1, COL9A2 and COL9A3 were highly suggestive in humans." (PMID 19284518, 2009).
myxoma (1 paper, 2024). A benign soft tissue neoplasm characterized by the presence of spindle and stellate cells, lobulated growth pattern, and myxoid stroma formation. "Fibroblasts within myxomas exhibit an activated state, characterized by elevated expression of well-known activated fibroblast markers 18such as POSTN, NOX4, FAP, and COL1A2." (PMID 39090109, 2024).
nasopharyngeal carcinoma (1 paper, 2013). A carcinoma arising from the nasopharyngeal epithelium. "miR-29 targeted several extracellular matrix genes including COL1A2, COL3A1 and COL5A2, and has been validated in nasopharyngeal carcinomas and HTM (human trabecular meshwork) cells." (PMID 24079748, 2013).
nephrolithiasis (1 paper, 2017). The presence of a calculus in the pelvis of the kidney; this is most often composed of mineral salts and proteins. "Genes encoding for Runx1, Runx2, KRT 18, KRT 8, VIM, Fn-1, Col1a1 and Col1a2 were up regulated during hyperoxaluric conditions and further increased after crystal deposition or nephrolithiasis." (PMID 29091707, 2017).
non-small cell lung carcinoma (1 paper, 2021). A group of at least three distinct histological types of lung cancer, including non-small cell squamous cell carcinoma, adenocarcinoma, and large cell carcinoma. "Type I collagen (COL1A1 and COL1A2) was correlated with the resembling of TAMs in non-small cell lung carcinoma (NSCLC) while it was not correlated with the paucity of T-cell accumulation in pancreatic ductal adenocarcinoma (PDAC), which were consistent with our results." (PMID 33543230, 2021).
orchitis (1 paper, 2021). Inflammation of one or both testes due to viral or bacterial infections. "In all the collagen members detected to be expressed in Lc, the expression profile shifted greatly during EAO, and Col3a1, Col4a1, and Col1a2 became the main collagens expressed during orchitis." (PMID 35111154, 2021).
Osteoblastoma (1 paper, 2015). A rare benign bone-forming neoplasm usually arising from the spine. "Expression of COL1A2 was very low in all cell lines as compared to osteoblastoma and normal growth plate controls (data not shown)." (PMID 25895133, 2015).
pancreatic adenocarcinoma (1 paper, 2022). "We used Gene Expression Omnibus (GEO) database and identified six genes (COL1A2, ITGA2, ITGB6, LAMA3, LAMB3, and LAMC2) that could affect the survival rate of pancreatic adenocarcinoma patients." (PMID 35899199, 2022).
parasitic diseases (1 paper, 2022). "COL1A1, COL1A2, and COL3A1 have been previously reported to be abnormally overexpressed in some tumors and parasitic diseases." (PMID 36034715, 2022).
pneumonia (1 paper, 2025). An acute, acute and chronic, or chronic inflammation focally or diffusely affecting the lung parenchyma, caused by an infection in one or both of the lungs (by bacteria, viruses, fungi, or mycoplasma.). "A 9-day-old male neonate with prenatally diagnosed COL1A2 (c.1459G > A, p.Gly487Arg) mutation was admitted to our NICU for respiratory distress and pneumonia." (PMID 41480373, 2025).
polyp (1 paper, 2023). A usually exophytic mass attached to the underlying tissue by a broad base or a thin stalk. "Loss of BMPR1A in Col1a2 expressing cells resulted in major histological changes in the colon and serrated polyp development in the small intestine." (PMID 36326956, 2023).
Pulmonary hemorrhage (1 paper, 2025). Pulmonary hemorrhage is a bleeding within the lungs. "Two novel and two pathogenic mutations in COL3A1 gene associated with vEDS, COL1A1, COL1A2, TNXB gene mutations of non-vascular types underlying EDS and COL4A2 gene associated with collagen synthesis were found in patients presenting with pulmonary hemorrhage." (PMID 40598578, 2025).
pulmonary neuroendocrine neoplasms (1 paper, 2023). "In a recent study, the up-regulation of six fibrogenic genes (COL5A2, COL1A2, COL3A1, ITGA5, ITGB1, and ITGB1) in pulmonary neuroendocrine carcinoma and the down-regulation of pulmonary neuroendocrine neoplasms were strongly related to no metastasis and overall survival." (PMID 37047300, 2023).
retinal degeneration (1 paper, 2023). Degeneration of the retina. "The results showed that proteins like CST3, C9, and ITM2B, among others, are associated with retinal degeneration while proteins such as COL1A2, IGFBP2, and AGT, among others, are associated with diabetic complications." (PMID 37884923, 2023).
Scheuermann disease (1 paper, 2021). A disorder characterized by osteochondrosis of the vertebral epiphyses in childhood. "It is speculated that the COL1A2 gene mutation might be an underlying novel genetic cause of Scheuermann’s disease." (PMID 34098919, 2021). "The detected COL1A2 gene mutation might be an underlying novel genetic cause of Scheuermann’s disease." (PMID 34098919, 2021).
schizophrenia (1 paper, 2023). A major psychotic disorder characterized by abnormalities in the perception or expression of reality. "Among the 7 DEGs, the TNC gene was the only gene that decreased with schizophrenia and showed a positive correlation with PI (16:0/20:4), while the other 6 DEGs (COL1A2, COL6A2, DDIT4, FGF17, GNB3, and PDGFRB) increased with schizophrenia and showed a negative correlation with PI (16:0 /20:4)." (PMID 37143779, 2023).
small bowel adenocarcinoma (1 paper, 2022). "Four target genes (APOA4, APOB, COL1A2, FN1) may be involved in the pathogenesis of small bowel adenocarcinoma." (PMID 36171259, 2022).
T-cell acute lymphoblastic leukemia (1 paper, 2021). Acute lymphoblastic leukemia of T-cell origin. "MiR-150 appears to modulate sialylation of EGFR via the PI3K/Akt pathway in T-cell acute lymphoblastic leukemia, and circRNA_000203 was found to promote cardiac fibrosis by suppressing targets of miR-26b-5p, Col1a2 and CTGF." (PMID 33494070, 2021).
tongue cancer (1 paper, 2021). A malignant neoplasm affecting the tongue. "We studied their expression in epithelial cells particularly and calculated an IRS to semi-quantify the expression levels of the COL1A2 and DCN protein in normal and tongue cancer cases for comparison with CRNN." (PMID 33889206, 2021).
vascular malformation (1 paper, 2023). A non-neoplastic disorder that is the result of defects of vascular morphogenesis. "COL1A2 is associated with cranial vascular integrity and can lead to vascular malformations." (PMID 37794518, 2023).
tumor (239 papers, 1988 to 2025). "CD93 plays a role in tumor-associated vasculature, and changes in Col1a2 expression have been observed after radiotherapy in other cancers." (PMID 40244686, 2025). "Functional analysis confirmed that ARRB1 and CTBP1/2 were associated with early tumor development, while COL1A2 and CEBPZ were involved in extracellular matrix remodeling and transcriptional regulation, respectively." (PMID 40362431, 2025). "Expression of collagen genes (e.g., COL1A1 and COL1A2) is induced in tumor stromal cells such as cancer-associated fibroblasts (CAFs) and in tumor cells by transforming growth factor beta 1 (TGFβ1)-mediated phosphorylated SMAD3 (pSMAD3) signaling." (PMID 39574893, 2024). "Our data further emphasize the essential role that cancer-associated, (universal) Col1A2-Cre-fibroblasts and extracellular matrix remodeling play in coordinating behavior among different cell types within the tumor microenvironment." (PMID 38363129, 2024). "To the best of our knowledge, for the first time, we predicted the ceRNA network of COL1A2 and explored its association with tumor immune infiltration and immune signatures." (PMID 37805556, 2023). "For the first time, we constructed a ceRNA prediction network of COL1A2 and explored the association of COL1A2 with tumor immune microenvironment remodeling." (PMID 37805556, 2023). "To the best of our knowledge, for the first time, we predicted the ceRNA network of COL1A2 and explored its association with tumor immune microenvironment remodeling." (PMID 37805556, 2023). "These secondary analysis results of external scRNA-seq data further confirm that these COL1A1+/COL1A2+/IGFBP2+ fibroblast-like cells are tumor associated and play a central role in the TME of brain metastasis tissues." (PMID 37479733, 2023). "Firstly, we had a general overview of COL1A2 from the following aspects: the differential mRNA expression of COL1A2 in various tumors, the location of COL1A2 protein in human tumor cells, and the different mutation types related to the COL1A2 gene." (PMID 36057263, 2022). "Age, chemotherapy, tumor stage, COL1A2, and CALD1 were significantly associated with worse prognosis (P < 0.05)." (PMID 33996905, 2021). "COL1A2 encodes the alpha-2 chain of type I collagen, a key component of the extracellular matrix; its overexpression may facilitate tumor invasion and has been linked to reduced overall survival in GBM patients." (PMID 41179304, 2025). "Moreover, the association of COL1A2 with tumor immune infiltration and immune signatures in COAD is still not determined." (PMID 37805556, 2023). "However, no studies, to the best of our knowledge, have reported the ceRNA network of COL1A2 and its association with tumor immune infiltration and immune signatures." (PMID 37805556, 2023). "Moreover, this research investigated the association of COL1A2 with tumor immune infiltration and immune signatures in COAD." (PMID 37805556, 2023). "Our data show that expression of EWSR1-FLI1 is associated with the strong production of collagens col1a1b, col1a2, col2a1a, col9a1b, col9a2, and col28a2a both in embryos and in advanced tumors (data not shown), suggesting the importance of specific matrix for tumor development." (PMID 35285802, 2022). "Although SLC25A21, EGFR, and COL1A2 are linked to tumour-associated signalling pathways, the precise mechanisms of this synergy remain unclear." (PMID 36246603, 2022). "Destruction of structural protein COL1A2, and loss of tumour related proteins CRNN and DCN support the speculation that all three are involved in a pathway for TSCC genesis." (PMID 33889206, 2021). "Interestingly, an mRNA transcript leading to type I collagen production, COL1A2, has been associated with proliferative events and markers of aggressive tumor biology, including epithelial to mesenchymal transition." (PMID 27895310, 2017).
tumor (continued). "Using the reads mapping to the transcript encoding for the reporter (dsRED) we selectively identified the tumor cells, which we found to express a mesenchymal signature of transcripts encoding for extracellular matrix genes and collagens (Col1a1, Col1a2, Cald1, Calu)." (PMID 38509063, 2024). "Furthermore, our findings showed that COL1A2 positively associated with immune infiltration and that tumor immune escape might be involved in COL1A2-mediated carcinogenesis in COAD." (PMID 37805556, 2023). "Three type VI COLs (encoded by COL6A1, COL6A2, and COL6A3) and two type I COLs (encoded by COL1A1 and COL1A2) constituted a significant proportion of the human colon ECM in NAT (55.6%) and tumor (31.8%) tissues." (PMID 40032993, 2025). "Specifically, MYOC, TBK1, COL1A1, and COL1A2 were upregulated in tumor tissues, while FOXC1, LRP2, and TEK was downregulated (all p < 0.05)." (PMID 40808675, 2025). "This COL1A2–ECM–FAK cascade mediates crosstalk between matrix cancer-associated fibroblasts and epithelial cells undergoing EMT, thereby facilitating tumor invasiveness." (PMID 41561769, 2025). "They identified, among others, Dcn, Sparc, Col1a2, and Col3a1 as significantly upregulated in CTCs compared to the primary tumor." (PMID 40227761, 2025). "The canonical markers EPCAM and KRT19 identified tumor cells, while CD3D, CD2, PTPRC, CD14, AIF1, CD79A, and COL1A2 validated non-tumor cells." (PMID 39955556, 2025). "In this study, we investigate the role of COL1A2 in ECM-related tumor biology and its potential as a prognostic biomarker for BCA progression." (PMID 41561769, 2025). "Top hits include changes in transcriptional regulation (ZNF385B, SNORA65), tumour microenvironment (COL1A2, COL3A1), and metastatic processes (UCHL1, SUCNR1, THY1)." (PMID 40890143, 2025). "Genes Ptgs2, Cxcl1, Vegfa, Cxcl2, Col1a1 and Col1a2 were downregulated in cluster 0 of the A101 CAR-T-treated tumor compared to the mock-T-treated group which are involved in angiogenesis and tumor-promoting inflammation as well as EMT and tumor progression." (PMID 40568084, 2025). "Collagen proteins (COL1A1, COL1A2, COL3A1, COL11A1) were associated with tumor progression and metastasis." (PMID 40867231, 2025). "The previous study highlighted the importance of hydroxyproline content, indicating that the presence of hydroxyprolines on peptides from COL1A1 and COL1A2 determined their histopathologic location in inflammatory regions (less HYP) or tumor (more HYP)." (PMID 39347566, 2024). "Taken together, the evidence highlights the importance of COL1A2 in various cancers, with its dysregulation contributing to tumor aggressiveness and metastasis." (PMID 38913913, 2024). "And The COL1A2 gene, as the marker gene for fibroblasts, was presented more higher expression in the tumor tissue." (PMID 39138733, 2024). "Single-cell analysis revealed high expression of SPHK1 in tumor cells (SOX2, KRT18) and cancer-associated fibroblasts (COL1A2 and MMP2) and low expression in cancer stem cells (PROM1)." (PMID 39629135, 2024). "In NED tumor tissues, which had far more variability in protein species detection, the top three most abundant species were also COL1A2, COL1A1, and COL3A1, respectively." (PMID 39347566, 2024). "Genes such as COL1A1, COL1A2, and COL3A1, which are implicated in the tumor microenvironment, and immune-related genes, such as THY1, IRF5, and HLA-DRA, exhibited significant expression level changes." (PMID 38672562, 2024). "When 5-FU was treated alone or in combination with iRGD or/and 5-FU, CoL1a1 and CoL1a2 gene expression was significantly reduced in the tumor tissues (P<0.001)." (PMID 37396945, 2023).